IL2 (interleukin 2)
Diseases named in the same sentence as IL2 in open-access papers (continued):
Sharing a sentence is not in itself a finding about the gene and the disease.
breast carcinoma (237 papers, 1988 to 2026). "Correlation analysis between plasma cytokine levels and clinicopathological features revealed that elevated levels of IFN-γ, IL-1β, IL-2, IL-6, and IL-12 (p40) were significantly associated with advanced clinical stages of breast cancer (P < 0.05)." (PMID 40612845, 2025). "More research is needed to evaluate our findings of elevated EV IL-2 associated with age in patients diagnosed with breast cancer." (PMID 35547250, 2022). "Next, focusing on data from the entire cohort of patients with breast cancer, we found that high coexpression of IL-31Ra, IL-4, IL-2, and Granzyme B was associated with increased survival, with results almost reaching statistical significance (p=0.056)." (PMID 32843492, 2020). "For example, breast cancer cells expressing IL2 were shown to cause the expansion of NKT-cells in vitro." (PMID 32560387, 2020). "Other studies have shown that the activation of the IL–2 signaling pathway is associated with proliferation of breast cancer cells." (PMID 29725024, 2018). "They suggested that the variants of ERCC2, TLR4, IL-2, IL-6, and IL-21 genes had associations with breast cancer prognosis respectively." (PMID 25075970, 2014). "The master activation factor IL-2, which mediates pro- and anti-inflammatory immune responses and promotes the proliferation and differentiation of natural killer (NK) and helper/regulatory T cells, is also linked to bone metastases in breast cancer." (PMID 40584290, 2025). "However, since Ki-67 is associated with poor breast cancer prognosis and our study showed that IL-2 levels correlated with tumor aggressiveness, the relationship between Ki-67 and IL-2 in breast cancer tumors warrants further investigation." (PMID 40869161, 2025). "Furthermore, elevated IL-2 levels in cases of breast cancer with bone metastases have been linked to the activation of anti-tumor immune responses." (PMID 40869161, 2025). "Furthermore, interleukin (IL)-17 and IL-2 were the most common cytokines linked to γδ T cells and our investigation of their potential involvement in the prognosis of gastric and breast cancers, identified their different roles in various malignancies." (PMID 35493488, 2022). "IL-2, a master activation factor for helper/regulatory T-cell and natural killer (NK) cell proliferation and differentiation, acting as a mediator for pro- and anti-inflammatory immune responses, is also associated with breast cancer bone metastases." (PMID 31847214, 2019). "Most of the trials focused on IL-2 and IL-12, used alone or associated with other drugs, to eradicate tumor cells by blocking blood flow to the tumor and by soliciting patient white blood cells to destroy breast cancer cells." (PMID 31847214, 2019). "In this study, fermented mung bean treatments in vivo were studied by monitoring tumor development, spleen immunity, serum cytokine (interleukin 2 and interferon gamma) levels, and spleen/tumor antioxidant levels after injection with low and high risk 4T1 breast cancer cells." (PMID 23710232, 2013). "Previous to the ex-vivo approach we aimed to find common targets between IL-2 and breast cancer disease using network pharmacology." (PMID 42192107, 2026). "Breast cancers cells obtained were then cultured in the presence of 10 μl of (50 ng/ml) recombinant IL-2 for 24 h." (PMID 42192107, 2026). "An intriguing aspect of this analysis is the pairwise error analysis which reveals the elevated potential for IL-2 versus IL-4 signal misidentification in CD4 + T cells in breast cancer patients." (PMID 41166390, 2025). "Here, we describe the construction, characterization, and use of VACV strains co-expressing murine Interleukin 2 (mIL2) and tumor-associated antigen (TAA)-derived epitopes as potential therapeutic agents against murine mammary carcinoma." (PMID 41050655, 2025).
breast carcinoma (continued). "Innovative exploratory study examining symptom-cytokine networks in breast cancer survivors; identified IL-2 and cognitive impairment as central; limited by a small sample size." (PMID 40633921, 2025). "For example, a preclinical study showed that in a mouse breast cancer model, lipid-coated biodegradable hollow MSNs co-loaded with interleukin-2 (IL-2), doxorubicin (DOX), and all-trans retinoic acid (ATRA) markedly improved antitumor immunity." (PMID 40872479, 2025). "Patients with breast cancer have been found to have significantly lower levels of circulating IL-2 and increased levels of circulating IL-4 when compared to healthy controls." (PMID 41150099, 2025). "Taken together, these data suggest that CD155.CAR T cells exhibit specificity and cytotoxicity against CD155+ cervical and breast cancer cells through greater secretion of IL-2 and IFN-γ." (PMID 41394877, 2025). "In the canine species, a study evaluating circulating cytokine profiles in healthy controls, mammary carcinoma in benign mixed tumor and mammary carcinoma, reported that IL-2 was higher in the latter group." (PMID 41150099, 2025). "TRUCKs have been developed to tackle a variety of malignancies, including glioblastoma, breast cancer, and other solid tumours, employing several cytokines such as IL-2, IL-12, IL-15, and IL-18." (PMID 39596267, 2024). "The resulting IL‐2‐Fc fusion protein was shown to have low toxicity and high antitumor efficacy in melanoma, colon cancer, and breast cancer models." (PMID 38317590, 2024). "Naringenin has been shown to decrease the infiltration of MDSCs and Treg cells in breast cancer cell lines, and to upregulate IL-2 and INF-γ -releasing T cells in spleen and lung tissue, demonstrating its use as an immunomodulatory agent." (PMID 39050852, 2024). "Regular exercise in breast cancer survivors after primary treatment has consistently shown to decrease pro-inflammatory cytokines (IL-2, IL-6, IL-8, TNF-α) and increase anti-inflammatory cytokines (IL-10)." (PMID 37507961, 2023). "Two breast cancer patients were enrolled in the high-dose cohort, receiving 7.8 × 1010 (plus three doses of IL-2) and 9 × 1010 (plus one dose of IL-2) cells with lymphodepletion." (PMID 38201551, 2023). "Some cytokines (leptin, IL-1β, IL-6, IL-8, IL-23, IL-17, TGF-β, IL-10) are mostly reported to stimulate while others (Il-2, IL-12, IFNs) inhibit breast cancer proliferation and/or invasion." (PMID 36835413, 2023). "The most frequently mentioned biomarkers for this cancer type came from the interleukin superfamily including IL-6, IL-8, IL-10, IL-2, IL-18, which is quite similar to what was found in breast cancer." (PMID 37181043, 2023). "The proposed strategy with additional INF-beta-IL-2 sequence in endocrine-dependent metastatic ER+ breast cancer patients seem to be effective, at least as effective as CDK 4/6 inhibitors but with a less harmful treatment profile." (PMID 38332913, 2023). "It was shown that, compared with healthy controls, in the saliva of breast cancer patients, there is an increase in the content of both pro-inflammatory (IL-2, IL-6, and IL-18) and anti-inflammatory cytokines (IL-4 and IL-10)." (PMID 36286034, 2022). "It was shown that in the group of breast cancer patients, only the content of IL-2 and IL-10 changed statistically significantly, and in both cases, there was an increase in concentration." (PMID 36286034, 2022). "Of note, we previously noted that single-agent taxane treatment increased serum IL-2 levels in patients with advanced breast cancer." (PMID 35799797, 2022). "The median survival of patients with breast cancer with low and high expression levels of IL-2 was 43 months and 56 months, respectively (HR = 0.86, p = 0.0031)." (PMID 35493488, 2022). "Interleukin-2: In a pilot study of patients with breast cancer, IL-2 was combined with granulocyte-colony-stimulating-factor (G-CSF) to mobilize immune effector cells." (PMID 35883639, 2022).
breast carcinoma (continued). "Intriguingly, antigen-activated T lymphocytes incubated with IL-7 and IL-15 exhibited a more robust capability to induce regression of melanoma and 4T1 mammary carcinoma in comparison to IL-2 alone." (PMID 36389666, 2022). "We have established that the level of IL-2 increases statistically significantly in the saliva of patients with breast cancer, and also increases at advanced stages of the disease." (PMID 36286034, 2022). "IL2 inhibited the growth of breast cancer cells through improving the proliferation of natural killer cells." (PMID 34983358, 2022). "To study immune-based mechanisms of long-term sustained synergy in in vivo models of breast cancer, we conducted immunophenotyping of IL-2, IFN-gamma, and THBS-4 in treated tumors with cytokine and Nanostring transcriptomic analysis." (PMID 35205763, 2022). "As a cytokine therapy for cancer treatment, IL-7 exerts superior activity to induce the expansion of specific T cells against breast carcinoma than IL-2, highlighting its antitumor adjuvant molecular role in oncology." (PMID 36389666, 2022). "Degranulation assays (CD107a) or cytotoxicity assays with the primary tumor cells as targets were performed by co-culturing these breast cancer cells with IL-2-activated NK cells as effector cells for 16 h." (PMID 34203549, 2021). "Further, therapy with cytokines, such as IL-2 gene therapy in a metastatic breast cancer model, can induce anti-tumor immunity that represses the growth of primary tumors or subsequent challenges." (PMID 33440806, 2021). "Donor-derived and IL-2-activated NK cells were co-cultured with patient-derived breast cancer cells or cell lines MCF7 or SKBR3 together with the anti-HER2 antibody trastuzumab." (PMID 34203549, 2021). "In this study, we showed that IL-2-activated NK cells can mediate anti-breast cancer responses under hypoxic conditions." (PMID 34203549, 2021). "T cells exposed to breast cancer cells can produce cytokines like IL-2, IFN-γ and TGF-β to mediate immune responses." (PMID 34959271, 2021). "Taken together, these results imply that IL-2-activated NK cells remained cytotoxic against the tested breast cancer cell lines under hypoxia." (PMID 34203549, 2021). "For example, administration of high-dose interleukin-2 in combination with lymphocyte-activated killer cells was ineffective in patients with breast cancer." (PMID 33579033, 2021). "γδ T cells isolated from breast cancer, lung cancer, ovarian cancer, colon cancer and other patients were found to effectively kill tumor cells or primary tumor cells when interleukin-2 (IL-2) was amplified in vitro." (PMID 34838003, 2021). "As a result, IL2-enriched membrane vesicles were able to activate and stimulate the proliferation of immune cells, which in turn were able to induce apoptosis in breast cancer cells." (PMID 33579033, 2021). "Our analysis of mRNA expression data sets revealed a positive correlation between survival and coexpression of IL-31Ra, IL-2 and IL-4 in breast cancer biopsies." (PMID 32843492, 2020). "The levels of cytokines IL-2 and IL-12p70 were higher in the controls than in patients with breast cancer who were receiving chemotherapy." (PMID 32703187, 2020). "There is a high induction of IL-2 in the breast cancer patients’ sera after one month following RT; however, this level returns to baseline after six months post irradiation." (PMID 31963587, 2020). "So far IL-2, IFNα, IFNβ and occasionally IFNγ, IL-6, IL-12 have been the cytokines used for anti-tumor treatment of advanced breast cancer either to induce or increase hormone sensitivity and/or to stimulate cellular immunity." (PMID 32887217, 2020). "Some of the strategies in breast cancer engineer the viruses to express immune stimulatory molecules or cytokines, such as IL-2, IL-12, and GM-CSF." (PMID 32937885, 2020).
breast carcinoma (continued). "In a separate study, adoptive transfer of haploidentical NK cells, pre-activated overnight with IL-2, showed a partial anti-tumor response in 20% of ovarian and breast cancer patients, and stable disease in 60% of patients." (PMID 31163679, 2019). "The fifth case was a breast cancer patient with distant metastases in CR, while receiving beta-interferon and interleukin-2 in addition to conventional hormone therapy." (PMID 31795079, 2019). "The synergistic effect of PPARγ ligands and GW9662 have been demonstrated in growth inhibition of breast cancer cells and suppression of IL-2 production in T-helper cells." (PMID 30400642, 2018). "Next, they started periodic subcutaneous injections of lipoplexes carrying a human granulocyte-macrophage colony stimulating factor and interleukin-2 mixed with allogeneic mammary carcinoma extracts." (PMID 30081470, 2018). "IL-18 added to IL-2 increases Vγ2Vδ2 T cell numbers by 2.7-fold after zoledronate stimulation of PBMC from breast cancer patients and increases the production of IFN-γ and TNF-α." (PMID 28239463, 2017). "Our data suggest that exogenous IL-2 is unnecessary for the assessment of γδTc cytotoxicity against breast cancer cell lines and indeed its propensity to drive activated T cells into apoptosis further warrants its exclusion from such assays." (PMID 28713391, 2017). "The antihuman CD25 mAbs basiliximab and daclizumab decrease Treg number and function by blocking IL-2 signaling; and daclizumab has been used to deplete Tregs and improve effector responses in human breast cancer vaccine trials." (PMID 28855899, 2017). "Another phase I clinical trial was conducted to test the safety and efficacy of HER2Bi-armed ATC in combination with interleukin 2 (IL-2) and granulocyte-macrophage colony stimulating factor (GM-CSF) in 23 patients with stage IV breast cancer." (PMID 28931402, 2017). "DLN T cells activated with B/I and cultured with IL-2, IL-21, IL-2/21, IL-7/15 or IL-7/15/21 for 7 days were harvested and cultured for 24 h alone or with irradiated 4T1 murine mammary carcinoma cells to stimulate IFN-γ release." (PMID 28146052, 2017). "DLN lymphocytes were antigen-sensitized with 4T1 mammary carcinoma 10 days prior to harvest, activated with B/I, and expanded in culture for 7 days with either IL-2, IL-21, IL-2/21, IL-7/15, or IL-7/15/21." (PMID 28146052, 2017). "IL-2 enhanced NK cell-mediated ADCC triggered by anti-HER2 mAb against breast cancer cell lines in vitro and in vivo." (PMID 29181007, 2017). "For instance, it has been reported that anergic T cells in breast carcinoma have defective IL-2 secretion." (PMID 28923084, 2017). "The mean survival time from first metastasis was significantly lower in breast cancer patients with reduced circulating IL-2 concentrations compared to those with normal IL-2 values, irrespective of response to therapy and dominant metastasis sites." (PMID 26970739, 2016). "In one study, LM murine fibroblast cells, genetically engineered to express interleukin-2 (IL-2), were transfected with genomic DNA isolated from a sporadic breast cancer in a C3H/He mouse before being injected into tumor-bearing C3H/He mice." (PMID 27669306, 2016). "In patients with advanced breast cancer, docetaxel therapy was associated with an increase in serum IFN-γ, IL-2, and IL-6 levels and enhancement of circulating NK cell activity." (PMID 27777963, 2016). "For example, adding interleukin (IL)-2 has been shown to enhance immunogenicity of a PS-targeting antibody for use as a breast cancer vaccine." (PMID 25815346, 2015). "Bozeman and colleagues used GPI to anchor IL-2 and IL-12 on the membrane of murine mammary tumor cells as a tumor vaccine." (PMID 26186692, 2015). "The up-regulation of the interleukin-2 (IL-2) and its receptor alpha (IL2RA) are associated with the malignancy of the infiltrating human breast cancer." (PMID 25077705, 2014).
breast carcinoma (continued). "Accordingly in breast cancer and B cell lymphoid cells with a very low basal expression, high protein levels of gp96 upon stimulation with the cytokines IL-2 and IFN-γ were detected." (PMID 24146856, 2013). "In this study, fermented mung bean in a dosage-dependent manner has delayed the formation of breast cancer and reduced the mitotic division of the tumor through stimulation of T cell cytokine production (IL-2 and IFN-γ) and cytotoxicity." (PMID 23710232, 2013). "IL-2 has been used to stimulate the immune system for the treatment of a number of different tumors, including breast cancer." (PMID 20953429, 2011). "In breast cancer patients, depressed serum levels of IL-2, GM-CSF, IFN-γ and enhanced TNF-α and IL-6 amounts were reported in comparison with controls and some of these immune dysfunctions are also present in early-stage tumors." (PMID 22112244, 2011). "MMTV.f.huHER2(Fo5) transgenic mice were immunized with scFv40 and scFv69 and, then, growth inhibition of spontaneous HER2-positive mammary tumors, humoral response, antibody isotype as well as splenocyte secretion of IL2 and IFN-γ were evaluated." (PMID 21294885, 2011). "This pilot clinical trial demonstrates that Her2-pDNA vaccination in conjunction with GM-CSF and IL-2 administration is safe, well tolerated and can induce long-lasting cellular and humoral immune responses against Her2 in patients with advanced breast cancer." (PMID 20529245, 2010). "In ER- breast cancer, IL12, IL2 and IFNG were significantly associated with good prognosis, while TGFB and EGFR pathway activation were associated with poor clinical outcome." (PMID 21050467, 2010). "We observed similar patterns of association in Set2, and in particular while IL12, IL2 and IFNG were associated with good prognosis in ER- breast cancer, IL13 correlated with poor outcome." (PMID 21050467, 2010). "The vaccine, encoding a full-length signaling-deficient version of the oncogene Her2, was administered together with low doses of GM-CSF and IL-2 to patients with metastatic Her2-expressing breast carcinoma who were also treated with trastuzumab." (PMID 20529245, 2010). "These levels of adenovirus-mediated IL-2 and IL-12 expression were effective in mediating tumour regression in a murine model of breast cancer." (PMID 17595664, 2007). "We conclude that oestradiol increases the cure rate of oestrogen-enhanced murine breast cancer treated with an intratumoral adenoviral vector expressing B7-1/IL-2." (PMID 12865933, 2003). "We have previously shown that adenoviral gene transfer of B7-1/IL-2 to murine breast cancer induces a high rate of complete tumour regression and systemic immunity." (PMID 12865933, 2003). "In this study, we demonstrated that oestradiol, at physiologic concentrations, enhances the immune response by intratumoral adenoviral gene delivery of B7-1/IL-2 in a murine model of breast cancer in which the growth rate is increased by oestrogen." (PMID 12865933, 2003). "Thus, ex-vivo approach was used to investigate IL-2 anti-tumor effect on breast cancer cells isolated from Egyptian patients after mastectomy via modulating Treg/CTLA-4/Blimp-1/caspase-3 trajectory." (PMID 42192107, 2026). "Additionally, Paciotti and Tamarkin reported that IL2 does directly inhibit the growth of human breast cancer cell lines in vitro and in vivo." (PMID 41050655, 2025). "It suggested that JCHAIN may play a key role in breast cancer through the IL2 and JAK-STAT pathways." (PMID 41010015, 2025). "In vitro 3D culture experiments demonstrated that when cultured in high-density and aligned ECM, CAFs can increase the expression of α-SMA and fibronectin while reduce the secretion of IL-2, thereby inhibiting T cell activation and accelerating breast cancer progression." (PMID 40890855, 2025). "Furthermore, by optimizing light exposure, LITS synergizes IL-2 efficacy by driving immunogenic cell death to eradicate lung metastasis in a breast cancer model." (PMID 40891669, 2025).